TNF (tumor necrosis factor)
Diseases named in the same sentence as TNF in open-access papers (continued):
Sharing a sentence is not in itself a finding about the gene and the disease.
brain injury (continued). "Inflammatory cytokines (IL-6, IL-10, and TNFα) were measured acutely in blood samples within 8 h following a medically diagnosed concussion and then 24 h later." (PMID 32450801, 2020). "In this study, we demonstrated that TNF-α pretreatment enabled hNPCs to survive longer after transplantation into HI brain injury and improved the neuroprotective effect of hNPC transplantation after focal HI brain injury." (PMID 32403417, 2020). "Brain injury induces the activation of M1 microglia and releases proinflammatory cytokines, such as TNF-α, IL-1β, and IL-6." (PMID 32922507, 2020). "Within the injured spinal cord and after traumatic brain injury, TNF-α and IL-6 are the two major cytokines produced by peripheral immune cells and activated glia adding to detrimental neuroinflammation." (PMID 33144615, 2020). "In a study of participants with traumatic brain injury, increased TNF-α in the CNS increased disinhibition (disinhibited behavioral state)." (PMID 32174860, 2020). "There is substantial evidence that pro-inflammatory cytokines, TNF-α, IL-1β and IL-6 can operate at very low concentrations on many cell types in the CNS or periphery, and can contribute to neurodegeneration in acute brain injury." (PMID 30682785, 2019). "Consistently, FN attenuated neuroinflammatory reaction through downregulating TNF-α and IL-1β and upregulating IL-10 in a rat model of traumatic brain injury." (PMID 31561418, 2019). "Elevated brain protein levels of TNF-α, IL-1β and IL-6 have also been detected in human CSF and serum after brain injuries." (PMID 30682785, 2019). "The inflammatory markers, such as microglia, ROS, IL-1β, and TNF-α, were detected in patents who experienced brain injuries." (PMID 29747437, 2018). "On the basis of these observations, we add evidence that pharmacological inhibition of TNF-α is a plausible treatment for acute diffuse brain injury." (PMID 29789012, 2018). "Functional roles for TNF-α, which is a pro-inflammatory cytokine, have been demonstrated in several I/R models, including those of I/R brain injury." (PMID 30151417, 2018). "The administration of TNF-α leads to an increase in tissue damage and neurological deficits, thereby aggravating ischemic brain injury." (PMID 28168001, 2017). "In ischemic brain injury, interleukin (IL)-6 and tumor necrosis factor alpha (TNF-α) are largely thought to act as pro-inflammatory cytokines which exacerbate brain damage and are involved in the initiation of early inflammation." (PMID 26690124, 2015). "In the present study, immunohistochemical staining and qPCR results demonstrated that the mRNA and protein expression levels of TNF-α and NF-κB in the hippocampal tissues increased following 24-h hypoxic-ischemic brain injury." (PMID 24940430, 2014). "Previous studies also reported elevated levels of inflammatory markers in blood following brain trauma, including IL-1, IL-6, IL-8, TNF-α and furthers." (PMID 23894384, 2013). "For example, in a rat Marmarou model of diffuse brain injury, TNF production is of a higher magnitude, and IL-1β expression is heightened and prolonged, when the injury is followed by a 30-min period of hypoxia." (PMID 23459929, 2013). "The synthetic cannabinoid, dexanabinol, which facilitated recovery and decreased cell death, reduced hippocampal expression of TNFα and IL-1β in the hippocampus after traumatic brain injury." (PMID 22537429, 2012). "Together with IL-1β and IL-6, TNF-α is one of the major pro-inflammatory cytokines released by activated microglia following ischemic brain injury." (PMID 17150094, 2006). "Tau also reduces TNF-α and IL-6, alleviating the severity of brain injuries." (PMID 39457890, 2024). "However, when comparing TNFα concentrations in the healthy group, we noted significantly lower levels (p = 0.0197), indicating a potential baseline difference in the context of brain injuries." (PMID 39540961, 2024).
brain injury (continued). "This ACh subsequently acts on α-7 nicotinic acetylcholine receptors (α-7nAChR), predominantly expressed on macrophages, leading to a reduction in pro-inflammatory cytokines such as TNF-α, IL-1β, and IL-6, thereby facilitating the recovery of neurological function following acute brain injury." (PMID 39723424, 2024). "However, following ischemic brain injury, the expressions of IL-1β and TNF-α were drastically increased in the microglia in the ipsilateral region, as shown by combined FACS and qPCR." (PMID 35968363, 2022). "Indeed, the levels of proinflammatory cytokines such as TNF-α, IL-1β, and IL-6 were significantly elevated in the early stage after brain injuries." (PMID 35163096, 2022). "Our study is the first to look at children with mTBI/concussion which shows priming of the TNF-α response from myeloid cells to LPS at two weeks, with an opposite and greater response to LPS challenge, at time when the majority of children appear to have recovered." (PMID 35130911, 2022). "In the CNS, both of these cytokines, acting through IL1R1s on astrocytes, endothelial cells, and neurons, initiate transcription of multiple pro-inflammatory cytokines, including TNFα, leading to reactive gliosis and enhanced neuronal excitability following such insults as traumatic brain injury." (PMID 34607558, 2021). "For example, this pathway is modulated in monocytes, macrophages and microglia by phosphodiesterase-4B (PDE4B), while treatment with a PDE4B allosteric inhibitor after acute brain injury reduces microglial activation, reduces production of TNF, and provides neuroprotective benefit in rats." (PMID 32203525, 2020). "Pro-inflammatory cytokines, such as TNF-α, IL-1β, and IL-6, are produced in the central nervous system and exert great effects on neuroprotection, which have been proven to be elevated in traumatic brain injury." (PMID 33791290, 2020). "Moreover, exosomes derived from exfoliated deciduous teeth stem cells have also been reported to inhibit IL-6 and TNFα production in LPS-stimulated BV-2 microglial cells and to dampen microglia activation in an animal model of traumatic brain injury." (PMID 30898154, 2019). "They found that a TNF-α synthesis inhibitor may mitigate secondary brain damage after a traumatic brain injury." (PMID 28404559, 2017). "Furthermore, they can secret proinflammatory cytokines such as TNF-α, IL-1β and IL-6 to recruit other immunocytes such as neutrophils and lymphocytes, which further aggravate brain injuries." (PMID 26086994, 2015). "It has been suggested that differential binding of TNF-α to these receptors may explain the differences between its early detrimental and delayed beneficial properties following concussion or more severe cases of TBI." (PMID 23248582, 2012). "It appears that central blockade of TNF-α following a concussion may prove to be beneficial, while prolonged antagonism could be detrimental." (PMID 23248582, 2012). "Accumulating data indicate that MnSOD is critical for neuronal survival against various stress-induced brain injuries, and that increased levels of TNFα in response to cytotoxic insults protect neurons in part via the induction of cytoprotective genes, including MnSOD." (PMID 21143912, 2010). "Such a "dual role" of TNF has been suggested previously in terms of concomitant pro- and anti-inflammatory effects and detrimental as well as beneficial neuroprotective properties after brain injury." (PMID 15285802, 2004). "Clinically established anti-TNF-α agents like infliximab, while primarily used for IBD, have shown efficacy in improving traumatic brain injury (TBI)." (PMID 41300453, 2025). "In this regard, specific proinflammatory cytokines, including IL-1β, IL-6, TNF-α, and IFN-γ, and markers of brain injuries, such as NFL and GFAP, have been proposed as etiological factors of SB/SI development." (PMID 38338174, 2024).
brain injury (continued). "A recent study in a repetitive mild non-invasive traumatic brain injury mouse model showed that saffron extract and crocin suppress TBI-induced inflammatory and oxidative responses by decreasing the levels of IFN-γ, TNF-α, MPO, GSH, and MDA." (PMID 36232902, 2022). "That is, TLR4 and C5aR1 represent an alternative upstream regulator in activating NF-κB by inhibiting cAMP/PKA signals and participate in TNF-α, IL-1β, and IL-6 production in MCAO/R-induced brain injury." (PMID 33633530, 2021). "By knocking out the HIF-1a gene, Helton found that HIF-1a reduced the expression of inflammatory mediators such as COX-2, tumor necrosis factor-alpha (TNF-alpha), and IL family proteins following hypoxic-ischemic brain injury." (PMID 33213432, 2020). "Therefore, TNF-α pretreatment may be a simple and safe approach to protect implanted hNPCs against HI conditions and improve the therapeutic effectiveness of hNPC-based cell therapy in HI brain injury." (PMID 32403417, 2020). "Circulating protein expressions of tau, NF-L, GFAP, TNFα, and IL8 were assessed in the two concussion cases." (PMID 29706930, 2018). "Gut barrier dysfunction and enhanced translation of NF-κB, TNF-a, IL-1b, IL-6, and ICAM-1 were observed in Nrf2−/− mice after traumatic brain injury." (PMID 27009867, 2016). "Electrical VNS against a burn injury model reduced serum levels of TNF-α and IL-6, and in a traumatic brain injury model, the suppressive effect of VNS on TNF-α was shown in intestine." (PMID 23424673, 2013). "PTX is known to inhibit TNF-alpha, PAF and phosphodiesterase inhibition has been proposed as an effective strategy to decrease the severity of neonatal hypoxic-ischemic brain injury." (PMID 23493977, 2012). "In addition, TNF-α increases PDE4B expression and nuclear translocation in microglia and PDE4B is highly expressed in activated microglia after traumatic brain injury and spinal cord injury." (PMID 37525115, 2023). "Knockdown of MyD88 attenuated the mRNA expression of TNF-α and inducible nitric oxide synthase (iNOS) in AD, while reduced inflammatory response was observed in MYD88 knockdown mice with traumatic brain injury (TBI)." (PMID 35873459, 2022). "RCT: Randomized controlled trial; TNF-α: Tumor necrosis factor α; TBI: traumatic brain injury; IL: Interleukin; GCS: Glasgow coma scale; GOS = Glasgow outcome scale; MRS = Modified Rankin scale; DRS = Disability rating scale; mTBI = Mild traumatic brain injury." (PMID 34405076, 2021). "Brain inflammation occurs in the damaged brain tissue following the infiltration of immune cells, which secrete proinflammatory cytokines tumor necrosis factor (TNF)-α, interleukin (IL)-1β, and IL-6 in ischemic brain injury, and this leads to the impairment of brain functions such as cognition." (PMID 33324357, 2020). "Previous experimental studies have shown that brain trauma initiates a cascade of multiple anti- and proinflammatory pathways with permeability-increasing properties, such as release of various cytokines such as IL6, TNF alpha, and IL10." (PMID 27822741, 2017). "Inflammatory mediators, including IL-1β, IL-6, IL-10, TNF-α and NF-κB were assessed to examine whether GLGZD was involved in the inflammatory response in ischemic brain injury." (PMID 25815894, 2015). "Furthermore, it has been shown that TNF-α acts synergistically with other proinflammatory cytokines; therefore, a consideration of these types of interactions is also necessary to fully understand the TNF-α contribution to the inflammatory response following a concussion." (PMID 23248582, 2012). "Plasma concentrations of TNF-α, IL-6 and CRP in subjects without injury or following control trauma and traumatic brain injury were determined." (PMID 23894384, 2013).
Chronic colitis (99 papers, 2008 to 2025). A chronic inflammatory disease of the large intestine (colon, cecum and rectum). "Chronic colitis has been shown to cause extensive epithelial damage, promote expression of pro-inflammatory cytokines like TNF, and increase epithelial cell turnover." (PMID 41282096, 2025). "It has been reported that this FRB supplementation inhibits TNF-α expression in DSS-induced inflammation in chronic colitis-associated extraintestinal manifestations and in streptozotocin-induced diabetic rats." (PMID 37447370, 2023). "Systemic and oral LMP-420 treatment for 16 days decreased colonic TNF levels in IL-10-deficient mice with chronic colitis, with a trend to decreased histologic inflammation for oral LMP-420." (PMID 18331642, 2008). "Moreover, the metalloprotease TACE, involved in the cleavage of membrane-bound TNF (mTNF) to produce soluble TNF (sTNF), also increased after chronic colitis induction in MCJ-deficient mice compared to WT, suggesting a higher sTNF/mTNF ratio." (PMID 35705557, 2022). "Collectively, our data suggest that the form of TNF highly affects disease severity during chronic colitis, and that sTNF could be linked to the amelioration of the MCJ-deficient phenotype reported in acute colitis." (PMID 35705557, 2022). "Similarly, intestinal organoids treated with low doses of pro-inflammatory IL-22 or the chronic colitis-associated cytokine TNF-α, displayed a small but significant increase in the percentage of Lgr5+ CBC cells." (PMID 32948837, 2020). "Hence, C. coli infection of aged conventional IL-10-/- mice with chronic colitis was associated with pronounced systemic TNF-α secretion." (PMID 32664563, 2020). "This system released over 70% of 5-ASA within 6–16 h at pH 7.0 and demonstrated therapeutic efficacy in a chronic colitis mouse model by significantly reducing the expression of IL-1β and TNF-α, as well as inflammatory markers such as MPO, H2O2, and MDA." (PMID 41219776, 2025). "In this study, we found that 5-ASA or monotropein remarkably decreased serum levels of TNF-a and IL-6 cytokines and increased levels of anti-inflammatory cytokine IL-10 in chronic colitis mice." (PMID 40041493, 2025). "In accordance with acute colitis, proinflammatory factor levels (e.g., IFN-γ, TNF-α, IL-17A, IL-1β and IL-6) were obviously elevated in chronic colitis mice compared to those of normal mice." (PMID 38396052, 2024). "In summary, our findings demonstrate that NIs improve DSS induced chronic colitis and reduce the expression of pro-inflammatory cytokines, such as TNF-α." (PMID 36678851, 2023). "Overall, the NI improved DSS induced chronic colitis by attenuating the mRNA expression of pro-inflammatory cytokines such as TNF-α." (PMID 36678851, 2023). "In a murine model of acute and chronic colitis, twice-daily α-MSH exposure was associated with an 80% reduction in fecal blood, reduced weight loss, and reduced TNF-α in the lower colon and nitric oxide production in the lower bowel." (PMID 36891301, 2023). "After treatment with various doses of PS-NPs, both rising TNF-α mRNA expression and declining IL-10 mRNA expression in mice with chronic colitis significantly aggravated, which was opposite to that of 5-ASA." (PMID 38110964, 2023). "It decreased pro-inflammatory cytokines (myeloperoxidase (MPO), nitric oxide (NO), and TNF-α secretion) in the colon during acute and chronic colitis." (PMID 38202328, 2023). "Compared to normal mice, the mRNA expression of TNF-α slightly increased while that of IL-10 significantly decreased in mice with chronic colitis." (PMID 38110964, 2023). "Cripto-1, as a multifunctional signaling molecule, exerts an extracellular immune effect through paracrine mode, such as regulating macrophage expression of proinflammatory cytokines TNF-α and IL-6, inducing chronic colitis." (PMID 36644162, 2023).
Chronic colitis (continued). "For mice with chronic colitis, plasma G-CSF and IL-6 were significantly increased in both females and males, while TNF-α and IL-17 were increased only in females." (PMID 35463755, 2022). "Infliximab also exhibited significant therapeutic activity in the chronic UC model, but AAV8-TBG-siRT+B+I ameliorated the manifestations of chronic colitis and restored the expression of TNF-α, B7-1 and integrin α4 to a better extent than infliximab." (PMID 36171212, 2022). "CGRP can induce the migration of T cell and the release of TNF-α by activating mast cells, and the blockage of the SP receptor can decrease the inflammation cells in mice with chronic colitis with T cell transfer." (PMID 35267319, 2022). "For mice with chronic colitis, plasma G-CSF and IL-6 were significantly increased in both females and males, while TNF-α and IL-17 levels were selectively increased in female mice." (PMID 35463755, 2022). "As expected, plasma levels of proinflammatory cytokines, including interleukin-6, interleukin-17, tumor necrosis factor alpha, and chemokine ligand 1, were significantly increased in the chronic colitis model." (PMID 36009796, 2022). "In the present study, we observed that plasma TNF-α and IL-17 were selectively increased in female mice with chronic colitis." (PMID 35463755, 2022). "These mice are characterized by a 69 bp deletion within the AU-rich element of the TNF gene, contributing to the overproduction of TNF, consequently leading to chronic colitis." (PMID 35003109, 2021). "One study, which used a specific ASO against murine TNF-α (ISIS 25302) at doses of 0.25, 2.5, and 12.5 mg/kg injected subcutaneously, reported a dose-dependent decrease in TNF-α mRNA expression in the colon and a decrease in the severity of chronic colitis." (PMID 33498456, 2021). "The mRNA expression levels of inflammatory cytokines including IFN-β, IL-1β, IL-6, iNOS, MCP-1, and TNF-α were high in AOM+DSS induced chronic colitis group." (PMID 33995655, 2021). "Akkermansia muciniphila can significantly alleviate DSS-induced chronic colitis by reducing the expression of TNF-α and IFN-γ, promoting the differentiation of Treg cells, and increasing the production of short-chain fatty acid." (PMID 34489916, 2021). "It is noted that activation of TNF-α signaling pathway plays a critical role during necroptosis and pathogenesis of chronic colitis." (PMID 33041798, 2020). "We next assessed both, large intestinal and systemic tumor necrosis factor-α (TNF-α) secretion in IL-10-/- mice with chronic colitis following C. coli infection." (PMID 32664563, 2020). "Taken together, Myricetin derivative M10 prevents DSS-induced chronic colitis through inhibiting the formation of necroptosis by down-regulating the TNF-α signaling pathway." (PMID 33041798, 2020). "There was also evidence that Akk exerted anti-inflammatory effects on chronic colitis as they improved clinical parameters and downregulated the expression of the proinflammatory cytokines including TNF-α and IFN-γ." (PMID 32832569, 2020). "Our previous study indicated that the KO mice developed spontaneous chronic colitis, which was characterized by the acquisition of IL-17A and TNF-α production in these animals." (PMID 32208434, 2020). "Consistent with other reports of chronic colitis, two key markers of chronic colitis IL-1β and TNFα were significantly elevated in PBS-treated mice when compared to healthy animals." (PMID 31756977, 2019). "TLR4 triggers elevated production of prostaglandin E2, influences epidermal growth factor receptor signaling (EGFR), and increases TNF-α/NOS2 induction in chronic colitis." (PMID 28408791, 2017). "The efficacy of IFX treatment was then investigated in vivo using a TNF‐α‐independent Trichuris muris‐induced infection model of chronic colitis." (PMID 27669117, 2017).